CASKIN2 (CASK interacting protein 2)
Synonyms: KIAA1139; FLJ21609; ANKS5B
Tractability: Antibody: the Human Protein Atlas places it where antibodies can reach. PROTAC: ubiquitination databases record sites on it.
Gene: Protein-coding gene on chromosome 17 (75,500,261 to 75,515,621, reverse strand). Ensembl gene ENSG00000177303.
Subcellular location: Cytoplasm
Subcellular location (Human Protein Atlas): Plasma membrane
Gene Ontology:
Biological process: signal transduction
Cellular component: plasma membrane; cytoplasm
Genetic constraint (gnomAD): Loss-of-function variants: 41 observed, 101.49 expected, observed/expected ratio (o/e) 0.4, 90% interval 0.31 to 0.52. The upper end of that interval is the gene's LOEUF score, 0.52, which puts it in group 2 of 6, group 1 being the genes least tolerant of losing a copy. Missense variants: 1,546 observed, 1,567.5 expected, observed/expected ratio (o/e) 0.99, 90% interval 0.94 to 1.03. Synonymous variants: 724 observed, 658.96 expected, observed/expected ratio (o/e) 1.1, 90% interval 1.03 to 1.17.
Homologues: Orthologues: chimpanzee CASKIN2 (99% identical), macaque CASKIN2 (98% identical), pig CASKIN2 (93% identical), dog CASKIN2 (92% identical), guinea pig CASKIN2 (90% identical), mouse Caskin2 (89% identical), rat Caskin2 (89% identical), tropical clawed frog caskin2 (50% identical), zebrafish caskin2 (50% identical). Paralogues in human: CASKIN1 (45% identical).
Diseases named in the same sentence as CASKIN2 in open-access papers:
CASKIN2 is named in the same sentence as 4 diseases in open-access papers, as found by Europe PMC text mining. Sharing a sentence is not in itself a finding about the gene and the disease. The quoted sentences say what the papers report.
depression (1 paper, 2022). "Neither CASKIN2 (log2FC = −0.016, p = 0.999), a protein-binding protein, nor TSEN54 (log2FC = −0.024, p = 0.999), a subunit of a tRNA endonuclease complex were differentially expressed in association with depression symptoms in the LOAD sample or the sex-stratified analysis." (PMID 36421693, 2022).
latent infection (1 paper, 2023). "On the other hand, the expression of lncRNAs lnc-XPNPEP1-5, lnc-CASKIN2-2, lnc-HSPA13-6, lnc-CLIC5-1, and LINC02502 was significantly reduced in both the latent infection group and the TB patient group compared to the uninfected HC group (all P-values < 0.05)." (PMID 38156018, 2023).
pancreatic adenocarcinoma (1 paper, 2023). "Another bioinformatic analysis with the TCGA and GEO datasets suggests that CASKIN2 expression is significantly associated with a lower risk with Pancreatic adenocarcinoma (PAAD)." (PMID 37296980, 2023).
tumor (1 paper, 2022). "CASKIN2, TLE2, USP20, SPRN, ARSG, MIR106B, and MIR98 were considered to be substantially expressed in the low-risk group, suggesting that these genes may be PAAD tumor suppressor genes." (PMID 35077391, 2022).